MIR2681 (microRNA 2681)
Synonyms: hsa-mir-2681
Gene: MicroRNA gene on chromosome 13 (101,967,642 to 101,967,746, reverse strand). Ensembl gene ENSG00000265164.
Homologues: Orthologues: chimpanzee MIR2681 (100% identical).